CDK1 (cyclin dependent kinase 1)
Diseases named in the same sentence as CDK1 in open-access papers (continued):
Sharing a sentence is not in itself a finding about the gene and the disease.
breast cancer (continued). "All the evidences implied RBM7 promoted breast cancer cell proliferation by stabilizing CDK1 mRNA via binding to AREs in its 3′-UTR." (PMID 33145401, 2020). "Expectedly, 8 of the 10 classifier genes were overexpressed as protein in breast cancers, including CDK1." (PMID 32424219, 2020). "We also found that both BECN1 and CDK1 are upregulated in breast cancer tissue compared with normal tissue." (PMID 32802407, 2020). "Based on integrated bioinformatic analysis, the present study has identified 321 DEGs and six hub genes (CDK1, CCNA2, TOP2A, CCNB1, KIF11, and MELK) that are associated with breast cancer tumorigenesis and progression." (PMID 31428132, 2019). "Silencing eIF3d in renal cell carcinoma is known to down-regulate the cell cycle B1/cyclin-dependent kinase-1 (CDK1) signalling pathway, and knocking down eIF3d in breast cancer cells inhibits the Wnt/β-catenin signalling pathway." (PMID 31118081, 2019). "In breast cancer and glioblastoma cells, miR-410-3p leads to growth inhibition through targeting CDK1." (PMID 31165412, 2019). "Stress hormones have been shown to mediate effects on the cell cycle in breast cancer cells, upregulating cyclin-dependent-kinase 1 (CDK-1), which lead to cell cycle progression through the G2/M stage." (PMID 35582576, 2019). "Genetic substitution of CDK1 gene has been shown to cause embryonic lethality, and its inhibition has been suggested as a potential therapy for MYC-dependent breast cancer." (PMID 30514202, 2018). "It has been shown that depletion of CDK1 or pharmacological inhibition of CDK1 sensitizes BRCA-proficient breast cancer to a PARP inhibitor." (PMID 30135856, 2018). "Together, these results indicate that the inhibition of PI3K or CDK1/12 can reverse the chemoresistance in tamoxifen-resistant breast cancer cells." (PMID 29686231, 2018). "At molecular levels, knockdown of UBAP2L increased p21 expression, but decreased the expression of CDK1 and Cyclin B1 in breast cancer cells." (PMID 29196913, 2018). "This study assessed the role of AR phosphorylation at ser81/ser515 and their two upstream effectors, cyclin-dependent kinase 1 (pCDK1) and extracellular-regulated kinase 1/2 (pERK1/2) in 332 ductal breast cancer patients by immunohistochemistry." (PMID 28415597, 2017). "Herein, we demonstrate that both p62/HDAC6-dependent autophagy and the aggresome pathway mediate CDK1 clearance in human breast cancer." (PMID 28855742, 2017). "For instance, Cks1 promotes cell to enter from G0 to G1 by mediating the ubiquitination of CDK1 inhibitor p130 in breast cancer." (PMID 28061788, 2017). "We found that chemotherapeutic agents or proteolytic stress in human breast cancer cells induced CDK1 degradation mediated by p62/LC3 and HDAC6." (PMID 28855742, 2017). "Specifically, breast cancer is one of the most common malignancies in women, and was used in this report as a model system to study CDK1 degradation via the lysosomal pathway." (PMID 28855742, 2017). "Complmentarity between CDK1 and three drugs, Aminophenazone, Pomalidomide and the Rosoxacin, implies novel pharmacological value of those drugs in breast cancer." (PMID 28977921, 2017). "In this report, we determine that both chemotherapeutic agents and proteolytic stress induce CDK1 degradation in human breast cancer MCF7 cells through p62/HDAC6-mediated selective autophagy." (PMID 28855742, 2017). "Among those five E2F targets correlated with malignant transition, Cdk1 and Plk1 were well studied in breast cancer, but much less so for Ccnb2, Aurkb, and Spag5 (7, 10, and 3 reports, respectively)." (PMID 28212608, 2017). "Previous report suggested that the knockdown of Cdk1 induced apoptosis in Myc-dependent human breast cancer cell." (PMID 27385216, 2016).
breast cancer (continued). "The Kaplan–Meier plots were generated by the mRNA expression levels of Cyclin B1 and CDK1 for OS of breast cancer patients who received adjuvant chemotherapy." (PMID 27486754, 2016). "PDCD4 inhibits CDK1 activity through induction of p21, and loss of PDCD4 is linked to breast cancer development." (PMID 26220712, 2015). "Indeed, induction of CDK1 has been linked to the growth of human colorectal cancer and acute myeloid leukemia; the reduction of p27 has been liked to the genesis and progression of a broad array of human cancers, including cancers of the breast, colon, prostate, ovary, lung, stomach, and others." (PMID 26687548, 2015). "Overall, these results suggest that further investigation of CDK1 inhibition as a potential therapy for MYC-dependent breast cancer is warranted." (PMID 24444383, 2014). "Upon treatment with the CDK1 inhibitor bohemine, there was a trend towards an increase in the number of endothelial and breast cancer cells present in both the S and G2/M phases of the cell cycle." (PMID 25393739, 2014). "A role for the CDK1/cyclin B1 complex in WA-dependent growth inhibition and G2/M cell cycle arrest in breast cancer cells has already been reported." (PMID 24498382, 2014). "Cdk1 has been identified as a clinically useful prognostic marker in non-small cell lung cancer, colon cancer, and breast cancer." (PMID 25511643, 2014). "Here we show that such dual inhibition of VEGFR2 and CDK1 kinase activity perturbs proliferation of breast cancer cells and is a potent anti-angiogenic agent, both in vitro and in an ex vivo murine model." (PMID 25393739, 2014). "As CDK1 is a major kinase partner to cyclin A1, our data show that altered expression of cyclin A1 also leads to an alteration in CDK1 expression in breast cancer cells." (PMID 23991063, 2013). "We found that changes in CDK1 specific activity after paclitaxel treatment predicted the paclitaxel sensitivity of breast cancer cells and xenograft tumors." (PMID 19239702, 2009). "Among the breast cancer xenograft tumors, however, tumors with significantly increased CDK1 specific activity after paclitaxel treatment were sensitive to paclitaxel in vivo, whereas tumors without such an increase were resistant to paclitaxel in vivo." (PMID 19239702, 2009). "Therefore, in the present study, we analyzed CDK1 expression in breast cancer using RNA-sequencing data from The Cancer Genome Atlas (TCGA) to compare its expression in normal and tumor tissues." (PMID 41278293, 2025). "Additionally, we explored the relationship between CDK1 expression and different breast cancer subtypes, focusing on ER, PR, HER2 status, and PAM50 molecular classifications." (PMID 41278293, 2025). "Additionally, Breast Tumour Kinase (BRK), a non-receptor type tyrosine kinase, has been found to confer resistance to tamoxifen treatment in breast cancer through the regulation of CDK1 tyrosine phosphorylation." (PMID 40275985, 2025). "This consistent overexpression suggests that CDK1 may function as an oncogenic driver in breast cancer progression." (PMID 41278293, 2025). "These immune cell types are often closely associated with anti-tumor immune responses, suggesting that high expression of CDK1 may affect breast cancer progression by regulating the activity of these immune cells." (PMID 41278293, 2025). "This differential expression pattern further suggests that CDK1 may play an important role in the molecular subtyping of breast cancer." (PMID 41278293, 2025). "AURKA and PLK1 are essential mitotic regulators that promote the G2/M transition and are often overexpressed in aggressive breast cancers, while CDC25C facilitates CDK1 activation and has been associated with unchecked cell cycle progression in high-grade tumors." (PMID 41017855, 2025). "In breast cancer, there is also evidence that the CDK1/CCNB1/PLK1 axis may be one of the potential pathways by which KIF2C affects tumor progression." (PMID 41333555, 2025).
breast cancer (continued). "Previous studies have confirmed that anticancer drugs can block mitotic progression by inhibiting the activity of the CDK1/Cyclin B complex, thereby inducing G2/M phase arrest, leading to a significant increase in the G2/M population and suppressing breast cancer cell proliferation." (PMID 40906079, 2025). "In another study, the proliferation of Michigan Cancer Foundation‐7 (MCF‐7) breast cancer cells was halted time‐dependently by mangiferin's suppression of the cyclin‐dependent kinase 1 (CDK1)–cyclin Bl signaling pathway and subsequent G2/M phase cell‐cycle arrest." (PMID 39479608, 2024). "CDK1 overexpression correlates with an adverse prognosis in breast cancer." (PMID 38547234, 2024). "According to a study, miR-424 may inhibit cell growth and arrest in cell cycle phases (particularly G2/M) in human breast cancer by negatively regulating cyclin-dependent kinase 1 (CDK1) mRNA, which may occur via the Hippo and ERK pathways." (PMID 37692482, 2024). "In this study, we further examined the clinical significance of a four-gene signature (comprising CDK1, PCNA, EZH2, and BUB1) that may be associated with relapse events in untreated luminal breast cancer patients." (PMID 38831458, 2024). "We examined this issue by reducing the prevalence of breast cancer samples (i.e., we only used a half number of breast cancer patients, including 606/1212 randomly selected patients), and we identified a new signature including 7 genes CDK1, AP1S1, CASP3, MAP1LC3A, SNCA, MAPT, and GSK3B." (PMID 38642129, 2024). "Also inhibiting CDK1 has been reported to induce apoptosis selectively in MYC-dependent breast cancer cells." (PMID 38246945, 2024). "CDK1 is involved in the control of events such as DNA replication, mRNA transcription and translation, DNA repair and cell morphogenesis, all of which are closely related to the development of breast cancer." (PMID 37667382, 2023). "Furthermore, KIAA1429 is sufficient to enhance the expression of CDK1 by an m6A-independent manner and further accelerates breast cancer progression." (PMID 37124622, 2023). "More intriguingly, the depletion of CDK1 significantly increased pVHL levels in other types of cancer cells including melanoma, pancreatic cancer, colorectal cancer, ovarian cancer and other kinds of human breast cancers." (PMID 36813923, 2023). "Furthermore, our research has shown that MELK, NUSAP1, and CDK1 are crucial hub genes that are overexpressed in breast cancer and have potential roles as biomarkers." (PMID 38084295, 2023). "In addition, CDK1 has been found in several tumor types, such as ovarian carcinoma, liver carcinoma, breast carcinoma, colorectal carcinoma, and prostate cancer." (PMID 37511023, 2023). "It has been previously reported that CDK1 promotes the migration and metastasis of cancer cells, e.g., colorectal carcinoma and breast cancer cells, by phosphorylating proteins such as EZH2 and activating pathways such as the Wnt/β-Catenin and ERK/GSK3β/SNAI axes." (PMID 35806389, 2022). "The present study convincingly revealed that d-limonene inhibits the growth of MCF7 breast cancer cells and arrest the cell cycle at the G2/M phase by inhibiting Cyclin B1/ CDK1 complex through their influential effect on structure and function leading to induction of apoptosis." (PMID 36307489, 2022). "CDK8, CDK7, CDK4, and CDK1 predicted unfavorable outcomes in luminal A breast cancer patients." (PMID 35628286, 2022). "CDK1 inhibitors may be particularly effective against aggressive breast cancers that express high levels of MYC, as the selective inhibition of CDK1 with purvalanol A triggers the apoptotic response in triple-negative tumor xenografts." (PMID 35408915, 2022).
breast cancer (continued). "Direct inhibition of CDK1 elicits potent anti-cancer activities in breast cancer cells." (PMID 36517522, 2022). "On the other hand, NCAPD2 could affect tumor cell proliferation, apoptosis, migration and invasion by targeting CDK1 in breast cancer." (PMID 35927248, 2022). "CDK1 is currently considered the best CDK target for breast cancer therapy." (PMID 33462336, 2021). "CDK1 mRNA could also been stabilized in an m6A‐independent manner by KIAA1429 which could promote breast cancer." (PMID 33259133, 2021). "Moreover, KIAA1429 acts as an oncogenic role by regulating cyclin-dependent kinase (CDK1) in a m6A-independent manner in breast cancer." (PMID 33796449, 2021). "The other study showed CDK1 acted as a novel prognostic indicator for early breast cancer." (PMID 33867838, 2021). "High expression of CDK1 was reported in breast cancer compared with normal tissue." (PMID 33816496, 2021). "Moreover, a flavone compound from Urginea indica bulbs tends to stimulate apoptosis, G0/G1phase arrest, and also inhibits angiogenesis in breast cancer cells by restricting CDK1 and CDK6." (PMID 34361615, 2021). "Furthermore, CDK1 was over expressed and had values on estimating prognosis of different kinds of cancers, such as ovarian cancer, breast cancer, hepatocellular cancer, gastric cancer and lung cancer 42-49." (PMID 33758599, 2021). "It is reported that KIAA1429 promotes breast cancer progression by regulating CDK1." (PMID 34281544, 2021). "For example, as CDK1 is known to be enriched in many cancer types, including breast cancer, pancreatic ductal adenocarcinoma, oral squamous cell carcinoma, and hepatocellular carcinoma, consideration of CDK1 as a potential biomarker may be advisable." (PMID 34063993, 2021). "Indeed, CDK1 overexpression has been demonstrated in various tumors, including melanoma, pancreatic cancer, colon cancer, and mammary carcinoma." (PMID 33982750, 2021). "Using Kaplan-Meier mapping instrument to access the gene chip database, we found that CDK1, PLK1, and CDC20 are associated with poor prognosis of breast cancer, which suggests that these three genes may be valuable genes." (PMID 32848800, 2020). "It indicated CDK1 was a main target of RBM7 exhibiting its oncogenic activity in breast cancer." (PMID 33145401, 2020). "G2-M regulation mediated by CDK1 has widely been studied for cancer therapeutics in breast cancer." (PMID 32331421, 2020). "Additionally, Qian and colleagues reported that KIAA1429 can regulate CDK1 in breast cancer in an m6A-independent manner, and act as a carcinogenic factor." (PMID 32111180, 2020). "In addition, high expression of CDK1 led to worse 5-year RFS in breast cancer patients, similar to the experimental results." (PMID 33083112, 2020). "Finally, IHC revealed that CDK1 expression was higher in RBM7 higher expressed breast cancer tissues (*P < 0.05)." (PMID 33145401, 2020). "Also, in experiments performed by the Western blot technique, it was found that the expression levels of cyclin A, cyclin B, and cyclin-dependent kinase-1 (CDK1) were repressed by apigenin treatment in human breast cancer cell line MDA-MB-231." (PMID 33195038, 2020). "Studies have shown that CDK1 is active in the cell cycle of several tumor-regulating cell adhesion and can be used as clinical prognostic biomarkers for nonsmall cell lung cancer, colon cancer, breast cancer, and ovarian cancer." (PMID 31737652, 2019). "Ubiquitin peptidase also affected p21 expression in breast cancer cell which inhibited the activity of cyclin-dependent kinase 1 (CDK1), an essential regulator of mitosis as it controls the centrosome cycle as well as mitotic onset through forming a complex with cyclin A or cyclin B." (PMID 28403900, 2017). "We propose that the levels of CDK1 clearance could potentially be used as a predictive biomarker for the efficacy of breast cancer chemotherapy." (PMID 28855742, 2017).
breast cancer (continued). "Finally, complmentarity between CDK1 and three drugs, Aminophenazone, Pomalidomide and the Rosoxacin, implies novel pharmacological value of those drugs in breast cancer." (PMID 28977921, 2017). "In addition, CDK1 was optionally lethal to MYC-dependent human breast cancer cells, suggesting further investigation of CDK1 inhibition as a potential therapy for this type of breast cancer." (PMID 27149165, 2016). "Besides, CDK1 overexpression in cancer was shown also for oral squamous cell carcinoma, breast cancer, epithelial ovarian cancer, and hepatocellular carcinoma." (PMID 26912061, 2016). "Supporting the roles of ERLIN2 in stabilizing Cyclin B1 protein and enhancing Cyclin B1/Cdk1 function in breast cancer cells, levels of Cyclin B1 and phosphorylated Cdc27 were increased in ERLIN2-expressing MCF10A cells but decreased in ERLIN2-knockdown SUM225 cells, compared with their controls." (PMID 27462423, 2015). "Therefore, specific apoptotic pathways appear to be involved in CDK1 inhibitor-induced MYC-dependent cell death, providing a mechanistic insight into MYC-CDK1 synthetic lethality in breast cancer cells." (PMID 24444383, 2014). "We showed here that breast cancer cells were also selectively sensitive to CDK1 inhibition." (PMID 24444383, 2014). "Since understanding the role of individual CDK activities in specific tumour subtypes is essential to improve efficacy of CDK inhibitors in clinical practice, selective inhibition of CDK1 warrants further investigation as a potential therapy for MYC-dependent breast cancers." (PMID 24444383, 2014). "Collectively, this work supports that Spy1 is a unique activator of Cdk1 in breast cancer cells and may represent a valuable drug target and/or a prognostic marker for subsets of breast cancers." (PMID 22280365, 2012). "Similarly, the G2/M checkpoint regulators, cdk1 and cyclin B1, have been shown to be expressed at higher levels in more advanced breast cancer lesions." (PMID 22194735, 2011). "CDK2 knockdown caused G1 accumulation, whereas CDK1 depletion caused G2/M slowing, and dual CDK1/2 depletion resulted in further G2/M accumulation and cell death in both anti-estrogen-sensitive and resistant cells, confirming CDK2 and CDK1 as targets for breast cancer therapy." (PMID 20010939, 2010). "The results of the present study show that autophagy initiated by D-arabinose is accompanied by down-regulation of CDK1 and Cyclin B1 and up-regulation of p21 and p27, suggesting that D-arabinose may modulate autophagy via cell cycle regulators in breast cancer cells." (PMID 38789954, 2024). "Hence, the newly synthesized bioactive pyranopyrazoles could serve as better structures to develop CDK1 inhibitors against human breast cancer cells." (PMID 36672680, 2023). "Thus, the inhibition of CDK1 could improve the response of BRCA-proficient breast cancer cells to PARP inhibition." (PMID 36813923, 2023). "Importantly, CDK1 was identified to be upregulated in a variety of malignant tumors, such as colorectal cancer, prostate cancer, bladder cancer, ovarian cancer, and breast cancer." (PMID 36568241, 2022). "Together, these results suggested that treatment with NTX, PRO, and NTX + PRO downregulated the expression of cyclin B1, CDK1, and the phosphorylation of CDK1, which caused G2/M phase cell cycle arrest without displaying sub-G1 populations in all the breast cancer cells." (PMID 34638341, 2021). "Thus, increased expression of CDK1 in early recurrence breast cancer may explain Tamoxifen resistance by protecting tumor cells from antiestrogen-mediated cell death." (PMID 33432018, 2021). "Although it was composed of target proteins shared by the MCF7 and DG75 cell datasets, the CDK1/SKP1 proximal network had mostly interactions that were exclusive to the breast cancer or DG75 cell network, suggesting that its regulation by SYK could be different depending on the cell type." (PMID 33670716, 2021).